BCL6 (BCL6 transcription repressor)
Diseases named in the same sentence as BCL6 in open-access papers (continued):
Sharing a sentence is not in itself a finding about the gene and the disease.
COVID-19 (continued). "Evidence supports that as COVID-19 aggravates, germinal centers and BCL6 expression are lost." (PMID 34603282, 2021). "And in COVID-19, BCL6 inhibits the hyperinflammatory response through modulation of the STAT signalling pathway, and its activity is associated with lung injury degree and immunomodulation, but persistently high expression may be associated with worse prognosis." (PMID 39965013, 2025). "Also, assessment of Tfh subsets, Bcl-6 expressing Tfh and levels of neutralizing antibodies might give a clearer insight on their role in COVID-19 pathogenesis and their relation with recovery and hyperglycemia development." (PMID 35286241, 2022). "Whether Tfh cells serve a similar role of SARS-CoV-2 infection is unclear, as some studies have identified increased cytotoxic Tfh numbers in COVID-19 patients, while others have identified decreased Bcl-6+ Tfh numbers and decreased GC counts in similar patients." (PMID 33302366, 2020). "Despite the evaluated levels of circulating memory Tfh cells in both the lymph nodes and spleen of patients with COVID-19, Tfh cells with different phenotypes, CD4+ICOS+, CD4+ CXCR5+, and CD4+ Bcl-6+, were present at decreased levels." (PMID 34696395, 2021). "We started our investigation by analyzing F/GC B cell subsets in LD-LNs from COVID-19–infected individuals from 2 centers (CHUV and Northwestern University) by applying a mIF that allows for the simultaneous detection of CD20, Bcl6, and Ki67." (PMID 40924502, 2025). "In addition, we found that some TFs were differentially expressed in severe COVID-19, including TF upregulations of IRF7, SP100, HMGB2, and BCL6, and downregulations of FOS and JUNB." (PMID 38612651, 2024). "Interestingly, although with a lesser intensity, the upregulation of AREG, MAFG, MAFK, BCL6 and IL10 still persisted in monocytes of post-COVID-19 subjects." (PMID 34572439, 2021). "Direct comparison between COVID-19 LD-LNs, matched SD-LNs, and distal LNs revealed that COVID-19 may not induce a generalized RF Bcl6 immune reactivity in LNs from different anatomical sites." (PMID 40924502, 2025). "In NALT TFH cells, type I IFN response genes showed a negative correlation with BCL6 in COVID-19." (PMID 39890933, 2025). "Therefore, COVID-19 induces a unique LD-LN immune reactivity, regardless of the Bcl6 expression." (PMID 40924502, 2025).
endometriosis (28 papers, 2017 to 2026). The growth of functional endometrial tissue in anatomic sites outside the uterine body. "While BCL6 overexpression is most commonly associated with endometriosis in women with unexplained infertility, it is a marker of endometrial inflammation and progesterone resistance." (PMID 41517625, 2026). "Noninvasive biomarkers, such as screening tests for endometrial BCL6 overexpression, have shown promising results in improving the diagnostic accuracy of endometriosis." (PMID 41517625, 2026). "BCL6 testing has demonstrated high diagnostic accuracy for endometriosis, with reported sensitivity of 93% and specificity of 96%." (PMID 41517625, 2026). "KRAS activation in cells with positive progesterone receptors stimulates the expression of the BCL6 protein, which is implicated in the pathogenesis of endometriosis." (PMID 39903727, 2025). "The BCL6 protein, a transcriptional repressor implicated in cell proliferation and oncogenesis, has been linked to the pathogenesis of endometriosis." (PMID 39903727, 2025). "SIRT1, a histone deacetylase, has also been shown to be co-expressed with BCL6 and contribute to the inflammatory response associated with endometriosis." (PMID 38999962, 2024). "Non-invasive methods, including but not limited to saliva testing, endometrial function testing, the Nezhat Endometriosis Risk Advisor (EndoRA) mobile application, and BCL6 testing, can be highly suggestive of endometriosis." (PMID 38256580, 2024). "A biomarker of endometriosis, BCL6, was shown to be associated with poor outcomes in in vitro fertilization (IVF)." (PMID 38999962, 2024). "A high expression of BCL-6 in women with endometriosis has been associated with a decrease in progesterone activating and regulating receptors and the inactivation of progesterone in the endometrium." (PMID 37174948, 2023). "High expression of the gene encoding transcriptional repressor BCL6 (B-cell lymphoma 6) in the endometrium allows the detection of endometritis associated with endometriosis." (PMID 36135172, 2022). "BCL6 is a promising candidate as a unique diagnostic tissular biomarker for the detection of endometriosis in women." (PMID 36294483, 2022). "Elevated BCL6 and aromatase levels are associated with progesterone resistance and estrogen dominance in women with endometriosis." (PMID 36135172, 2022). "Previous work establishing BCL6 expression within the endometrium was based on the idea that endometriosis is associated with inflammation which includes upregulation of inflammatory cytokines." (PMID 34698105, 2021). "Increased BCL6 expression in the endometrium has been implicated in patients with unexplained or endometriosis-associated infertility." (PMID 32266059, 2020). "Rather than proceeding directly to empirically assisted reproductive technologies, clinicians could use a positive BCL6 result to justify earlier referral to endometriosis specialists for diagnostic laparoscopy." (PMID 41517625, 2026). "Additionally, the overexpression of B cell lymphoma 6 (BCL6) in the PF has been proven to promote the development of endometriosis and to be associated with endometriosis-related infertility." (PMID 36865552, 2023). "By using this original computer-assisted method, our work confirmed that endometrial BCL6 is proportionally expressed with endometriosis stage and that BCL6 overexpression is associated with endometriosis, especially with infertility caused by this gynecological disease." (PMID 36294483, 2022). "However, in the endometrium of women with stage IV endometriosis associated with infertility, the intensity distribution was spread out in a larger range between 26.138–125.93, indicating a higher and more heterogeneous BCL6 expression." (PMID 36294483, 2022).
endometriosis (continued). "The goal of our study was to determine if levels of SIRT1 and/or BCL6 were differentially expressed in any of these bodily fluids and could potentially be used as part of a less invasive diagnostic test for the presence of endometriosis." (PMID 34698105, 2021). "Among the 43 Receptiva group, 41 (95.3%) tested positive for endometrial BCL6 overexpression, yet all 43 (100%) were histopathologically confirmed to have endometriosis or endometrial-like glands and stroma." (PMID 41517625, 2026). "The ReceptivaDx TM (CiceroDx, Huntington Beach, CA, USA) test detects endometrial BCL6 overexpression in patients who were asymptomatic of endometriosis symptoms other than unexplained infertility or recurring failure in successful conception and implantation." (PMID 41517625, 2026). "Background/Objectives: Endometrial B-cell lymphoma 6 (BCL6) overexpression has been proposed as a marker of progesterone resistance, occult endometriosis, and endometrial dysfunction in infertile women." (PMID 42279583, 2026). "Future studies should investigate the expression of BCL6 in adenomyosis and endometriosis to further elucidate its role in uterine disorders." (PMID 39903727, 2025). "The expression level of BCL6 in the secretory phase was found to be higher in the eutopic endometrium in women with endometriosis and unexplained infertility than in that of fertile women." (PMID 40358172, 2025). "Another study concluded that women with suspected endometriosis and elevated BCL6 expression had lower assisted reproductive technology (ART) success rates compared to those who underwent medical or surgical therapy before embryo transfer." (PMID 38813329, 2024). "Interestingly, endometriosis-associated gene dysregulation in early secretory phase matches dysregulation in the transgenic mouse endometrium in the present study in terms of affected gene-set, above all the progesterone-regulated genes (e.g. Errfi1, Bcl6, Cited2, Irs2, Tgfb2, Gpx3, Tk1)." (PMID 38346980, 2024). "High BCL6 expression in the endometrium is an indicator for the presence of inflammation and endometriosis, and predicts unexplained IVF failure." (PMID 38999962, 2024). "Increased endometrial BCL6 and BCL9 levels are considered to be a non-invasive diagnostic marker for endometriosis." (PMID 39684461, 2024). "BCL-6 is thought to be responsible for progesterone resistance in the endometrium of women with endometriosis." (PMID 37174948, 2023). "The overexpression of BCL6 appears to result from the phosphorylation of STAT3 in the eutopic endometrium of women with endometriosis." (PMID 37108154, 2023). "A high BCL-6 HSCORE is generally used to detect both occult endometriosis and the development of progesterone resistance." (PMID 37174948, 2023). "Several recent studies have investigated the relationship between the expression rate of BCL-6 in the endometrial gland epithelium and endometriosis." (PMID 37174948, 2023). "In order to further study the role of BCL6 in endometriosis-related infertility, a comparison of its expression in the endometrium of infertile patients without and with endometriosis was performed on a second set of patients." (PMID 36294483, 2022). "Using the cutoff value of 1.4 in HSCORE analysis, BCL6 expression displayed an accuracy of 94% for diagnosing endometriosis." (PMID 36294483, 2022). "We find a higher expression of BCL6 in the endometrium of infertile women with endometriosis and women with stage IV endometriosis." (PMID 36294483, 2022). "We recently described the association of BCL6 and SIRT1 as potential mediators of progesterone resistance in women with endometriosis." (PMID 34698105, 2021). "SIRT1 has been found to be overexpressed in the endometrium of women with endometriosis and co-expressed with BCL6." (PMID 34698105, 2021). "The average serum concentration of BCL6 in serum for patients with stages I or II of endometriosis was 1645.7 pg/mL with a sample size of ten." (PMID 34698105, 2021).
endometriosis (continued). "In patients with unexplained or endometriosis-related infertility, an increased BCL6 expression has identified the endometrium." (PMID 35054432, 2021). "Since both SIRT1 and BCL6 are differentially expressed in the eutopic endometrium of women with endometriosis, these two proteins were chosen for our study using ELISA assay of bodily fluids including serum, plasma, urine, saliva, and cervical swab." (PMID 34698105, 2021). "Other authors looked into the role of BCL6 expression in the endometrium and the likelihood and or relation of progesterone resistance in women with endometriosis as possible predictors of implantation failure." (PMID 35054432, 2021). "The elevation of SIRT1 serum levels in stages III/IV follows the prediction by earlier studies of endometriosis which anticipated a rise in markers of inflammatory cascade such as BCL6 and SIRT1." (PMID 34698105, 2021). "The authors suggest that KRAS, SIRT1, and BCL6 are coordinately over-expressed in the eutopic endometrium of women with endometriosis and likely participate in the pathogenesis of endometriosis." (PMID 33435147, 2021). "Our study explored the utilization of B-Cell Lymphoma 6 (BCL6) and Sirtuin 1 (SIRT1) as potential biomarkers in serum, plasma, urine, and cervical mucus for a non-invasive diagnostic test for endometriosis." (PMID 34698105, 2021). "One effect of STAT3 overexpression in endometriosis appears to be the up-regulation of the oncogenic gene repressor B cell CLL/lymphoma 6 (BCL6), a known target of STAT3 and shown to be increased in the secretory phase endometrium of women with endometriosis." (PMID 31387263, 2019). "We report here for the first time in endometrium, direct protein-protein interactions between SIRT1 and BCL6 in human endometrial tissue, co-localizing in the nuclei of endometriosis cases." (PMID 28754906, 2017). "Recently, we reported that BCL6 is highly over-expressed in endometrium from women with endometriosis during the secretory phase of the menstrual cycle compared to women without endometriosis." (PMID 28754906, 2017). "We believe SIRT1/BCL6 represent a more proximal defect in endometrium of women with endometriosis that interferes with early signaling of P4." (PMID 28754906, 2017). "Since both proteins appear to be elevated, we analyzed the relationship between SIRT1 and BCL6 proteins in eutopic endometrium of endometriosis patients." (PMID 28754906, 2017). "In this study, we demonstrated for the first time that SIRT1 is over-expressed in women with endometriosis compared to controls by western blot and immunohistochemistry, correlating directly with elevated BCL6 expression." (PMID 28754906, 2017). "Together, these data suggest that KRAS, SIRT1 and BCL6 are coordinately over-expressed in eutopic endometrium of women with endometriosis and likely participate in the pathogenesis of endometriosis." (PMID 28754906, 2017). "Further, elevated levels of SIRT1 and BCL6 in secretory phase endometrium of women with endometriosis likely accounts for the decrease noted in GLI1 protein expression, as a sign of P4 resistance." (PMID 28754906, 2017). "Our results showed a strong positive correlation between SIRT1 and BCL6 levels in women with endometriosis throughout the menstrual cycle phases (n = 44)." (PMID 28754906, 2017). "The levels of SIRT1 and BCL6 proteins were significantly increased at 9 and 15 months post-inoculation during endometriosis progression." (PMID 28754906, 2017). "The immunofluorescence results show that SIRT1 and BCL6 proteins were co-localized in endometrial epithelial cells of endometriosis patients." (PMID 28754906, 2017). "Perhaps most striking was the concurrent up-regulation of both proteins in baboon model of endometriosis, both BCL6 and SIRT1 appearing within 9 months of induction of the disease." (PMID 28754906, 2017).
endometriosis (continued). "The findings established BCL6 as a novel diagnostic marker, demonstrating an area under the curve of 94% for differentiating patients with and without endometriosis." (PMID 41517625, 2026). "Indeed, multiple studies have validated the clinical utility of BCL6 testing for endometriosis diagnosis." (PMID 41517625, 2026). "In this study of 195 patients with unexplained infertility and confirmed endometriosis, those who underwent preoperative Receptiva BCL6 testing had significantly fewer affected anatomical sites and a lower proportion of high-stage disease compared to those who did not undergo testing." (PMID 41517625, 2026). "BCL6 may therefore be a candidate biomarker for endometriosis and endometrial dysfunction, including progesterone resistance." (PMID 40358172, 2025). "Deeper understanding is also required regarding the role of BCL6 in the non-malignant diseases where it has been implicated, such as pre-eclampsia, endometriosis, and ischemic stroke." (PMID 39456751, 2024). "Another study reported that elevated endometrial BCL6 levels could be used as a positive predictive factor for diagnosing endometriosis in women who undergo in vitro fertilization (IVF)." (PMID 38813329, 2024). "Epithelial BCL6 expression levels were found to be comparable in the endometrium of control women and of women with endometriosis stage I. However, higher BCL6 glandular epithelial cell expression was observed in the endometrium of infertile women with stage IV endometriosis." (PMID 36294483, 2022). "Recent studies have identified a promising tissular biomarker called B-cell lymphoma 6 (BCL6), which could be used to diagnose women affected by endometriosis." (PMID 36294483, 2022). "Indeed, we found that endometrial BCL6 expression was higher in the endometrium of women with stage IV endometriosis." (PMID 36294483, 2022). "The use of molecules targeting BCL6 could be a new approach to be investigated in order to treat these numerous patients suffering from endometriosis." (PMID 36294483, 2022). "In addition, studies suggest that IL-6 is upregulated in endometriosis patients, which leads to downstream signaling of pSTAT3 and BCL6." (PMID 34698105, 2021). "The authors observed a correlation between SIRT1 and BCL6 expression in endometriosis." (PMID 33435147, 2021). "Thus, a correlation between endometriosis, inflammatory cascades, and subsequent elevation in BCL6 levels was suggested." (PMID 34698105, 2021). "Thus, both SIRT1 and BCL6 over-expression can be regulated through inflammatory cytokines known to be present in women with endometriosis." (PMID 28754906, 2017). "In addition, like BCL6, they appear to be specific endometrial biomarkers for the diagnosis of endometriosis." (PMID 28754906, 2017). "This is based, in part, on evidence that endometrial biopsy-based testing for BCL6 and SIRT1 is predictive for the presence of endometriosis in women with infertility." (PMID 38999962, 2024). "Another previous study demonstrated that Sirtuin 1 (SIRT1) and BCL6 overexpressed and suppressed the promoter of GLI1, contributing to progesterone resistance and the pathogenesis of endometriosis." (PMID 36865552, 2023). "B Cell lymphoma 6 (BCL6), a transcriptional gene repressor and a target of STAT3, has been shown to be upregulated in endometriosis." (PMID 37108154, 2023). "Both SIRT1 and BCL6 bind to the GLI1 promoter and suppress its expression, leading to a reduction in GLI in women with endometriosis." (PMID 37108154, 2023). "Previous studies demonstrated that endometrial B-cell lymphoma-6 (BCL6) protein levels are significantly higher in patients with RPL, unexplained infertility or endometriosis (eutopic endometrium) when compared with controls." (PMID 35146127, 2022). "This project aims to determine if differential expression of B-Cell Lymphoma 6 (BCL6) and Sirtuin 1 (SIRT1) proteins can be used as a marker to aide in the diagnosis of endometriosis through less invasive means." (PMID 34698105, 2021).